KRT5 (keratin 5)
Diseases named in the same sentence as KRT5 in open-access papers (continued):
Sharing a sentence is not in itself a finding about the gene and the disease.
influenza (23 papers, 2013 to 2025). An acute viral infection of the respiratory tract, occurring in isolated cases, in epidemics, or in pandemics; it is caused by serologically different strains of viruses (influenzaviruses) designated A, B, and C, has a 3-day incubation period, and usually lasts for 3 to 10 days. "In human patients with severe influenza or COVID-19 infection, extensive expansion of dysplastic KRT5+ cells correlates with long-term compromised lung function after viral clearance." (PMID 39352385, 2024). "The ectopic expansion of dysplastic KRT5+ cells in lung alveoli has been reported in patients after influenza or COVID-19 infection." (PMID 39352385, 2024). "Recent studies have shown that p63+Krt5+ distal airway stem cells (DASCs) undergo proliferative expansion in response to influenza-induced lung injury and assemble into nascent alveoli at sites of interstitial lung inflammation." (PMID 37741976, 2023). "Specifically, there was a significant induction of Krt5 following Flu infection, which is of particular interest as it is a marker for lung multipotent basal cells." (PMID 38092883, 2023). "It is reported that Notch signaling initiates the expansion of LNEPs to basal-like Krt5+ cells in an alveolar remodeling following H1N1(PR8) influenza infection in a HIF1A dependent manner." (PMID 35130980, 2022). "Similar to the EBC-derived tuft cells in influenza-infected mice, the ectopic tuft cells in the parenchyma of COVID-19 lungs co-expressed KRT5 and POU2F3, suggesting a similar differentiation scheme." (PMID 36129169, 2022). "p63+ LNEPs are defined by the high expression of CD14 and activate the ΔNp63/Krt5+ remodeling program after bleomycin or influenza injury." (PMID 35406531, 2022). "Distinct tuft cell populations derived from Krt5+ cells arise in the lung following influenza clearance." (PMID 36073526, 2022). "We recently described the emergence of tuft cells within Krt5+ dysplastic regions after influenza injury." (PMID 36073526, 2022). "(E) Representative immunostaining of tamoxifen-treated Krt5-CreER tdTomato lungs 25 days post influenza." (PMID 36073526, 2022). "Here, we found that aged animals displayed an increased percentage of Krt5+ cells during the recovery phase of influenza-induced lung injury, which reflects the dysregulated repair response among aged hosts." (PMID 33600379, 2021). "In previous studies, investigators demonstrated that after influenza-induced lung injury, a population of cytokeratin 5+ (Krt5+) basal-like cells expand and migrate to the distal airspaces in an attempt to repair the injured epithelial barrier." (PMID 33600379, 2021). "Severe influenza infection leads to a robust expansion of Krt5+ cells, which migrate distally to form cyst-like structures or pods intended to cover the damaged alveolar wall." (PMID 33600379, 2021). "Instead, the accumulation of Krt5 + progenitor cells has been observed following influenza infection." (PMID 34158111, 2021). "A KRT5 lineage-tracing model was utilized to isolate DASCs which were transplanted into syngeneic mice infected with influenza." (PMID 31455003, 2019). "In our sub-lethal influenza pneumonia model, we observed the formation of DASCs (expressing P63 and KRT5) that started migrating out from the bronchioles from 9 dpi, giving rise to obvious DASC pods at 11 dpi, which was also previously reported." (PMID 31455003, 2019). "Several studies demonstrated that P63+/KRT5+ mDASCs underwent rapid proliferation and migration to damaged alveolar regions in response to influenza-induced ARDS." (PMID 31159891, 2019). "Krt5+ distal airway stem cells are essential for lung regeneration after influenza infection." (PMID 38061015, 2024). "However, recent studies showed that following respiratory viral infections, such as influenza and Sendai virus, a group of rare distal airway progenitor cells are activated and repair the injured alveoli with KRT5+ dysplastic cells." (PMID 39352385, 2024).
influenza (continued). "Thus, a population of immature, distal stem cells positive for keratin 5 (KRT5) and tumor protein p63 (p63) expands and mobilizes to the alveolar region after influenza infection forming dysplastic KRT5+/p63+ pods able to regenerate lung parenchyma." (PMID 37191411, 2023). "As tuft cell differentiation is more heterogeneous in bleomycin compared with influenza, we investigated whether tuft cells are involved in preventing normal alveolar differentiation in Krt5+ areas." (PMID 36073526, 2022). "Furthermore, WNT/β-catenin signaling induced by hypoxia was reported to promote the ATII reconstruction and blockade the Krt5+ basal-like activation from LNEPs for alveolar regeneration in influenza injured mouse lungs." (PMID 35130980, 2022). "Relatively few double-positive cells were observed in regions of alveolar destruction (zone 4), and we chose to focus on zones 1–3, as Krt5+ cell expansion after influenza infection has been reported to result in hypoxic vasoconstriction in regions of severe alveolar damage." (PMID 32091393, 2020). "Moreover, using multiple lineage tracing strategies, Sox2+ lineage‐negative progenitor cells were shown to be the main source of emerging Krt5+ cells in influenza‐induced lung injury, whereas Sox2+Krt5+ resident basal cells made a significantly minor contribution." (PMID 41318981, 2025). "After influenza infection, DCLK1+TRPM5+ SCCs coexpress p63 and arise near Krt5+ cells, suggesting a common origin with p63+Krt5+ distal airway epithelial cells implicated in lung regeneration." (PMID 38061015, 2024). "Krt5+ basal cells migrate to damaged alveolar regions and transdifferentiate into AT2 and AT1 to recreate an epithelial barrier under influenza-induced acute lung injury." (PMID 35406531, 2022). "(A–P) Lung sections stained for Krt5 in green, Dclk1 in red, and DAPI in blue 22–25 days after influenza." (PMID 36073526, 2022). "(A–B, D–E) Lung sections stained for Krt5 in green, Dclk1 in red, DAPI in blue 22 days after influenza infection." (PMID 36073526, 2022). "Histologically, influenza- but not SARS-CoV-2-infected mice showed extensive Krt5+ “pods” structure co-stained with stem cell markers Trp63/NGFR proliferated in the pulmonary consolidation area at both 7 and 14 DPI, with regression at 21 DPI." (PMID 38092883, 2023). "We found that in Pou2f3-/-, Trpm5-/-, and Il4ra-/- animals, the percent of Agr2+ area within Krt5+ area was not significantly different from controls following influenza infection." (PMID 36073526, 2022). "In one report, Krt5 + cells have been shown to accumulate in the lung-damaged areas, and may give rise to both ATI and ATII cells following severe influenza infection." (PMID 34158111, 2021). "Furthermore, in response to major lung injury, regardless of the model (bleomycin‐induced or influenza infection), repair is predominantly mediated by a preexisting population of ΔNp63+Krt5− cells, later defined as lineage‐negative epithelial progenitors (LNEPs)." (PMID 41318981, 2025). "However, subsequent studies using fate-mapping approaches have demonstrated that regeneration of the alveolar epithelial lineages by airway cells expressing Krt5 does not occur at a substantial frequency following influenza infection (reviewed comprehensively in 57)." (PMID 36270292, 2023). "Transcriptomic analyses revealed that compared to influenza-infected mice, SARS-CoV-2-infected mice had reduced interferon-gamma/alpha responses at 4 DPI and failed to induce keratin 5 (Krt5) at 6 DPI in lung, a marker of nascent pulmonary progenitor cells." (PMID 38092883, 2023).
urothelial carcinoma (22 papers, 2014 to 2025). A malignant neoplasm derived from the transitional epithelium of the urinary tract (urinary bladder, ureter, urethra, or renal pelvis). "Consistent with the basal differentiation in Kmt2c/d KO urothelium, the urothelial carcinoma models exhibited basal phenotype, corroborated by KRT5 positivity and loss of UPK2 by IHC." (PMID 39806204, 2025). "KRT5/6-positive highly malignant urothelial carcinoma was infiltrated by immune cells at 17.1 ± 1.4% level, whereas in low-grade basal NMIBC, CD8+ cells occupied only 5.1 ± 0.8% of tumor area (p = 0.001)." (PMID 32455829, 2020). "CK5/6 IHC was performed by using FLEX Monoclonal Mouse Anti-human Cytokeratin 5/6, clone D5/16 B4 (Lot No. 20042129) by DAKO envision method according to manufacturers protocol on 127 cases of urothelial carcinoma (on representative tissue blocks)." (PMID 29587848, 2018). "UC1/p-UC1 and UC2/p-UC2 expressed only luminal markers (KRT7, GATA3), supporting their classification as luminal-type urothelial carcinomas, while UC3/p-UC3 expressed basal markers (KRT5, KRT6) and KRT7 but lacked GATA3 and keratinization markers, confirming its basaloid subtype." (PMID 41387887, 2025).
lung squamous cell carcinoma (18 papers, 2008 to 2025). "In the mouse lung squamous cell carcinoma model, the protein in the lung squamous cell carcinoma cells can strongly express KRT5/14." (PMID 36056339, 2022). "A suspected driver of lung squamous cell cancer (SCC) is basal cells, as a primary characteristic of lung SCC is basal cell metaplasia and increased expression of canonical basal cell markers like KRT5, SRY-box 2 (SOX2), and tumor protein p63." (PMID 39337350, 2024). "Exosomal TP63, KRT5, CEACAM6, and SFTPB mRNAs can be used as biomarkers to differentiate between lung squamous cell carcinoma (LUSC) and lung squamous cell carcinoma (LUAD), thereby, providing a novel strategy for their differential diagnosis and treatment." (PMID 35584089, 2022). "Positive staining for Keratin 5, Keratin 6, Keratin 14, or TP63 can indicate squamous cell carcinomas of the lung." (PMID 25955027, 2015). "Therefore, we selected SOX2, KRT5 and KRT14 stemness gene proteins, PD-L1 immune related proteins, vimentin protein, and EpCAM protein, all of which influence epithelial carcinogenesis, to explore whether the mechanism at the cell level corresponds to lung squamous cell carcinoma pathogenesis." (PMID 36056339, 2022).
pulmonary fibrosis (18 papers, 2018 to 2025). Chronic progressive interstitial lung disorder characterized by the replacement of the lung tissue by connective tissue, leading to progressive dyspnea, respiratory failure, or right heart failure. "Our findings suggest KRT17+KRT5– cells represent a convergent pathogenic mechanism in lung fibrosis, making them attractive therapeutic targets for CLAD, where treatment options remain severely limited." (PMID 41122970, 2025). "Idiopathic pulmonary fibrosis has been associated with aberrant expansion of KRT5-expressing basal cells." (PMID 37758700, 2023). "Aberrant expansion of KRT5+ basal cells in the distal lung accompanies progressive alveolar epithelial cell loss and tissue remodelling during fibrogenesis in idiopathic pulmonary fibrosis (IPF)." (PMID 37758700, 2023). "The accumulation of undifferentiated Krt8hi transitional cells and/or the emergence of Krt5−Krt17+ aberrant basaloid cells and ectopic Krt5+ pods are hallmarks of lung injury, and their persistence have pathologically been associated with chronic diseases such as lung fibrosis." (PMID 38077031, 2023). "Previous studies have shown that Pla2g10 expression increases in ciliated cells and KRT5−/KRT17+ cells but decreases in AT2 cells in a bleomycin-induced pulmonary fibrosis mouse model, with symptoms improving after intervention." (PMID 40278587, 2025). "Loss of Sox2 promotes KRT17+KRT5– dysplastic epithelium after injury in the distal lung that is present in IPF lungs and patients with post-COVID-19 pulmonary fibrosis." (PMID 39927460, 2025). "This was characterized by an increase in aberrant basaloid (Krt8) and/or basal cells (Krt5) and increased pulmonary fibrosis based on hydroxyproline content compared to control lungs." (PMID 40343336, 2025). "These cells were first identified in single-cell studies as KRT17+/KRT5- basaloid cells in human idiopathic pulmonary fibrosis (IPF) lungs and independently shown by in vitro studies to arise from AT2 cells." (PMID 37830426, 2023). "Single cell analysis of human lung fibrosis recently identified a disease specific cell state that was termed aberrant basaloid cell (KRT17+/KRT5-) based on some similarities to airway basal cells." (PMID 32678092, 2020). "Indeed we observe increased bronchiolization based on Krt8 and Krt5 expression and increased pulmonary fibrosis based on hydroxyproline content in Adrp-CreERT2;Mycf/f;mTmG mice 6 weeks after bleomycin injury." (PMID 40343336, 2025). "If validated, the identification of KRT17+KRT5− basaloid cells or profibrotic alveolar macrophages in bronchoscopic biopsies may assist in identifying patients with irreversible lung fibrosis in the future." (PMID 33257409, 2020). "Intriguingly, though Yap deletion affects the maintenance of dysplastic KRT5+ cells, the lung fibrosis was not ameliorated." (PMID 39352385, 2024). "However, for those patients with severe lung diseases such as acute respiratory distress syndrome, idiopathic pulmonary fibrosis, and COPD, it is observed that the P63+ KRT5+ cells would appear in alveolar spaces, suggesting their possible participation of lung repair or regeneration process." (PMID 39566467, 2024). "We and previous studies found that there are P63+ and/or KRT5+ cells enriched in the damaged alveolar region of many lung disease patients (including those with COPD, pulmonary fibrosis and bronchiectasis), which could be the progeny of endogenous SOX9+ BCs in the middle of differentiation process." (PMID 29344809, 2018).
skin tumors (17 papers, 2010 to 2025). "Besides that, ASIP was strongly linked with BCC, MM, and other malignant skin neoplasms, and KRT5 with BCC and other malignant skin neoplasms." (PMID 39003418, 2024). "Immunofluorescence staining of tail epidermis whole mounts revealed that the BCC-like lesions in the three mouse models were positive for the basal keratinocyte marker keratin 5 (K5) and the basaloid skin tumor marker keratin 17 14 (K17)." (PMID 40060632, 2025). "The correlations of ASIP and KRT5 with the three types of skin cancer remained consistent with the initial analysis results." (PMID 39003418, 2024). "This multidimensional approach nominates ASIP, KRT5, CTSS, and TNFSF8 as potential diagnostic and therapeutic targets for skin cancers." (PMID 39003418, 2024). "Proteins, ASIP, KRT5, CTSS, and TNFSF8, have the potential as diagnostic and therapeutic targets for skin cancers, and validation through future biological experiments is required." (PMID 39003418, 2024). "Whereas TRF2 over-expressing mice under the 5′-regulatory region of the keratin 5 (K5) gene have increased vulnerability to spontaneous skin tumors and are sensitive to UV-induced carcinogenesis." (PMID 34947936, 2021). "Remarkably, as skin cancer can originate from KRT5-positive basal stem cells, the strategy of BMP inhibition proved also effective in this tissue." (PMID 32894216, 2020). "ASIP was colocalized with all three types of skin cancer and STX8, KRT5, GSK3A, CTSS, and TNFSF8 with BCC." (PMID 39003418, 2024). "These antibodies are essential for identifying various skin tumors and include markers such as S-100, HMB-45, Melan-A, Cytokeratin 5/6, and Ber-EP4." (PMID 39061614, 2024). "Overexpression of IGF-1 in the keratin 5 (K5) positive epidermal basal cells activates IGF-1R signaling, which promotes downstream mitogenic and cell survival signaling, resulting in spontaneous skin tumor formation." (PMID 35401828, 2022). "Pathologists should not be quick to jump to a diagnosis of NUT carcinoma for a skin tumor featuring abrupt keratinization, immunohistochemical evidence of squamous differentiation (positive cytokeratin 5/6 and/or p63), and NUT expression, as the poroid family of skin tumors may share these features." (PMID 34898574, 2021).
invasive breast carcinoma (15 papers, 2006 to 2025). A carcinoma that infiltrates the breast parenchyma. "However, we did detect rare ciliated cancer cells present in patients with invasive breast cancer and found that these express a marker of basaloid cancers that is associated with poor prognosis (Cytokeratin 5)." (PMID 24987519, 2014). "The rare ciliated cancer cells found in invasive breast cancer samples frequently co-expressed cytokeratin 5 (CK5)." (PMID 24987519, 2014).
malignant mesothelioma (13 papers, 2011 to 2025). A malignant neoplasm of the pleura or peritoneum, arising from mesothelial cells. "Primaquine targets KRT7, a novel interactor of KRT5, whose high expression has been correlated with tumour aggressiveness and drug resistance in malignant mesothelioma." (PMID 33916178, 2021). "Histopathologic examination confirmed malignant mesothelioma of epithelioid type, supported by immunohistochemical reactivity for calretinin, cytokeratin 7 (CK7), cytokeratin 5/6 (CK5/6), pan-cytokeratin (PanCK), Wilms tumor 1 (WT1), and loss of BRCA1-associated protein-1 (BAP1)." (PMID 40978995, 2025).
ovarian carcinoma (13 papers, 2008 to 2026). A malignant neoplasm originating from the surface ovarian epithelium. "KRT5 deficiency can prevent the migration of ovarian cancer cells, which prompts that it may act as an oncogene." (PMID 34980950, 2021). "In ovarian cancer cell line SKOV3, KRT5 and KRT7 were upregulated by Forkhead box M1 (FOXM1) and KRT5 and KRT7 deficiency prevented migration." (PMID 34070214, 2021). "KRT5 and KRT6 (KRT6A, KRT6B & KRT6C) gene expression was assessed in publically available serous ovarian cancer data sets, ovarian cancer cell lines and primary serous ovarian cancer cells." (PMID 28147318, 2017). "Using qRT-PCR KRT5 is expressed by metastatic OVCAR-5, OV-90, and SKOV-3 ovarian cancer cells, as well as by poorly metastatic OVCAR-3 cells but not the peritoneal cell line, LP-9." (PMID 28147318, 2017).
papilloma (13 papers, 2011 to 2023). A benign epithelial neoplasm that projects above the surrounding epithelial surface and consists of villous or arborescent outgrowths of fibrovascular stroma. "Increased susceptibility to papilloma was also observed in the transgenic mice that express IGF1 under keratin-1 or keratin-5 gene promoter." (PMID 30981207, 2019). "Mcpip1eKO papillomas were characterized by elevated transcriptional expression of Krt5, Krt13 and keratin 14 (Krt14), indicating a highly proliferative phenotype." (PMID 34903245, 2021). "Keratin 5 was diffusely expressed in the trichoblastomas but primarily in the basal cells in papillomas." (PMID 25474466, 2014).